CD4 (CD4 molecule)
Diseases named in the same sentence as CD4 in open-access papers (continued):
Sharing a sentence is not in itself a finding about the gene and the disease.
tumor (continued). "High infiltration of stromal CD8+ immune cells, high infiltration of stromal CD4+ immune cells, high infiltration of both tumour and stromal CD8+ immune cells and high infiltration of PD-1+ and CD8+ immune cells were associated with longer OS in all subsets." (PMID 32433601, 2020). "It is not clear if, like in RA, citrullination triggers ENO1 autoantibodies in cancer patients, although citrullinated ENO1 was reported to elicit anti-tumor CD4+ T responses in murine tumor xenografts and in ovarian cancer patients." (PMID 33584813, 2020). "The absolute requirement of CIITA-driven MHC-II positive tumor cells to trigger tumor-specific CD4+ Th cells and initiate the cascade of events, leading to an efficient adaptive anti-tumor immune response raised several key questions." (PMID 33138029, 2020). "The tumor derived miR-214 can be transferred into the recipient CD4+T cells through microvesicles induces Treg expansion, thereby inducing immune suppression and enhanced tumor growth." (PMID 33614495, 2020). "Tumor-infiltrating leukocytes (TILs) comprised 16 ± 2% (mean ± sem) and 17 ± 2% of CD4+ and CD8+ T cells, respectively, and these proportions were not significantly different between the various treatment groups." (PMID 32917858, 2020). "T cells inhibiting the growth of dormant tumor cells, ex vivo, were predominated by CD4+ and CD8+ Te or Tem subsets." (PMID 33115528, 2020). "We estimated the relationship between the abundance of six types of tumor-infiltrating immune cells (B cells, CD4+ T cells, CD8+ T cells, neutrophils, macrophages, and dendritic cells) and PTPN6 expression values in BC." (PMID 32454905, 2020). "Quantification of immunolabelled cells in situ confirmed increased CD8+ CTLs and CD4+ Th cells, with FoxP3+ Treg cell numbers remaining unchanged in the Cx3cr1‐Rheb1Δ/Δ tumours." (PMID 32567735, 2020). "Unlike targeting with invariant chains, using neoantigens where T-cells were the only adaptive mediators of tumour resistance, it was observed that the effect of therapy was dependent on both CD4+ and CD8+ T-cells combined." (PMID 32650622, 2020). "Among lymphocytes, CD8+ and CD4+ T-cells are the main agents in anti-tumor response triggered by IRE." (PMID 32784598, 2020). "The significant correlation of CD8+ and CD4+ Yap-cKO gene signatures with tumor T-cell infiltration in TCGA data suggest that Yap represses CD8+ and CD4+ T-cell migration and tumor infiltration in human cancers." (PMID 31929526, 2020). "Recent experiments in murine cancer models showed that CTLA-4 blockade enhanced tumour immunity by improving the helper function of CD4+ T cells." (PMID 32708397, 2020). "SPP1 expression was weakly related to tumor purity together with the CD4 + T cell, macrophage, and DC infiltrating degrees in LUSC." (PMID 33324676, 2020). "The proportion of Macrophages M1, Tregs, CD8 T cells, Tfh cells, and activated memory CD4 T cells were increasing accompany with advanced tumor T stage; whereas resting memory CD4 T cells, resting dendritic cells, and resting NK cells were down-regulated." (PMID 33665156, 2020). "The proportion of CD4+CD25+Foxp3+ Treg in the transplanted tumor tissues of mice in the solanine treatment group was significantly lower than that in the control group." (PMID 33204731, 2020). "Analysis of the interaction among tumor infiltrating immune cells (e.g., DCs, MDSCs, CD4/8T cells, and Tregs), stromal cells, and tumor cells is essential to understand the relationship between the TME and the clinical effects of cancer immunotherapies." (PMID 33282961, 2020). "Tumour samples had a significantly higher level of stromal CD4+ TIIC densities than normal tissue (p < 0.05)." (PMID 33153211, 2020). "Recently, necroptotic cell death pathway was shown to be involved in tumor necrosis and high level of potassium released from necrotic tumor cells inhibits both CD4 and CD8 T cell activity leading to tumor development and metastasis 16,17." (PMID 32742497, 2020).
tumor (continued). "The fraction of GzmB-expressing CD4+ T cells was increased in the tumor following αCTLA-4 treatment in accordance with the TCR transgenic data." (PMID 31924474, 2020). "Tumor-infiltrating lymphocytes (TILs) differ from normal peripheral blood immune cells with respect to surface molecule expression, subtypes, and CD4+ and CD8+ T cell populations." (PMID 32000802, 2020). "Cytokine neutralization also promoted a significant increase in the frequency of tumor-infiltrating T lymphocytes: at least 2-fold for both CD4 and CD8 T cells." (PMID 33330068, 2020). "The immunological kinetics of neutrophil exactly matched the transition of the size of the skin lesion area in the MRSA-challenged site as well as the effector CD4+ T cell response." (PMID 32093163, 2020). "The results indicated that the recombinant MUC1-MBP vaccine enhanced MUC1-specific Th1 response and CTL killing activity, and increased the proportion of tumor infiltrating lymphocytes (CD4+ T and CD8+ T cells)." (PMID 32823603, 2020). "The Lgals9-based network by Cytoscape showed extensive and complex correlation between Lgals9 and other molecules in tumor-immune microenvironment, including CD4, CD19, CD79A, CIS, IL2RG, FCGR2C, and FASLG." (PMID 33082168, 2020). "In this work, we show an increased CD4+FOXP3+ T cell density in the tumour core correlated with prolonged survival and CD4+FOXP3+ T cells clustered with CD8+ T cells rather than tumour cells." (PMID 32377339, 2020). "In vitro, M‐CSF, TGF‐β and VEGF from primary tumor supernatants skewed the differentiation of healthy donor blood monocytes towards CD163highCD86lowIL‐10high M2‐like MΦ that strongly suppressed CD4+ T‐cell expansion via PD‐L1 and IL‐10." (PMID 32082570, 2020). "CCL14 showed strong correlation with tumor-infiltrating B cells, CD4+ and CD8+ T cells, macrophages, neutrophils, and dendritic cells." (PMID 31927532, 2020). "After tumor resection, an increase of CD4+ and CD8+ T cells and activated microglia was observed with a decrease of resting macrophages and resident microglia." (PMID 33374542, 2020). "γδ T cells that positively influence anti-tumor immunity express IFN-γ that serves to both activate antigen-experienced CD4+ and CD8+ αβ T cells and increase the expression of MHC-I molecules on tumor cells." (PMID 33324425, 2020). "Fewer CD8 and CD4 CAR T cells were detected in the tumor if Reovirus was administered 24–72 h prior to adoptive transfer." (PMID 32581235, 2020). "In the present study, the number of distant tumour-infiltrating not only CD11c+ and OX-62+ DCs but CD4+ and CD8+ T cells in the RFA-OK-432 group was higher than that in the control or RFA-only group." (PMID 32541941, 2020). "Amongst CD3+ T cells in MUM, CD8+ T cells seem to be present at the interface of tumor and normal liver whereas CD4+ T cells are more concentrated in the perivascular areas." (PMID 33317028, 2020). "The eradication of solid tumours by naive CD8+ T cells is dependent on help from tumour‐specific CD4+ T cells." (PMID 31803974, 2020). "An increase in CX3CL1 expression in a tumor is correlated with the anti-cancer response of the immune system—the accumulation of anticancer CD4+ T cells, CD8+ T cells, dendritic cells and NK cells in a tumor." (PMID 32466280, 2020). "Recent evidences suggest that HCC tumor microenvironment is enriched with Foxp3+CD4+ and PD-1+CD8+ T cells which together provide an extensive immunosuppressive microenvironment." (PMID 33014820, 2020). "Under NIR irradiation, tumor-bearing mice had higher activations of both CD4 and CD8 T cells in mouse spleens in treatment groups as well as an increase in IL-6, IL-12, and TNF-α in mouse serum." (PMID 33260534, 2020). "Hallmarks of effective vaccine immunotherapy will be the requirement to enhance the number and quality of tumor-infiltrating T cells and the induction of robust CD4+ and CD8+ T cell responses." (PMID 33298945, 2020).
tumor (continued). "In another study it was shown that CTLA-4 blockade leads to the enhanced proportion of IFN-γ producing CD4+ ICOShi effector T cells to Tregs in peripheral blood and tumor tissues of patients with bladder cancer." (PMID 33519807, 2020). "Recently, a cell population identified as CD4+ Foxp3-PD-1hi was demonstrated to suppress tumor-infiltrating and peripheral CD4+ and CD8+ effector T cells." (PMID 33008010, 2020). "Within the tumor microenvironment, tumor-infiltrating neutrophils (TINs) can suppress T cell functionality and promote the formation of pro-tumor CD4+ T regulatory cells." (PMID 33374595, 2020). "The increase in local recurrence was linked to a suppression of markers of CD4+ T cell antigen presentation and CD8+ T cell infiltration in the recurring tumors, indicative of reduced anti-tumor immunity." (PMID 32580156, 2020). "In the context of chemotherapy, a study provided evidence that the NLRP3 inflammasome including caspase-1 are important for the induction of tumor-specific IFNγ producing helper CD4+ T cells, since Th1 priming failed in NLRP3 or caspase-1 deficient mice." (PMID 32674488, 2020). "Taken together, the cytokine milieu in PDA biases CD4 T cells away from Th1 and toward Th2, Th17 and Treg which is beneficial for tumor growth." (PMID 33584701, 2020). "High tumor CD4+ T cell levels predict adverse tumor outcomes, particularly when coincident with low CD8+ T cell levels." (PMID 32244756, 2020). "Much work remains to determine the independent contributions of CD4 and CD8 T cells, the antigen-specificity of such T cells, and the mechanisms underlying tumor clearance." (PMID 33584701, 2020). "Murine tumor-infiltrating CD4+ Th9 cells were shown to kill advanced tumors because of their ability for expressing cytolytic granzymes." (PMID 32499786, 2020). "In vitro experimentations have shown that sPD-L1 is mainly released by tumor cells and mature dendritic cells and can induce apoptosis of CD4+ and CD8+ T lymphocytes." (PMID 32085544, 2020). "IL-1β stimulates dendritic cells (DCs) activation and tumor antigen presentation to CD4+ and CD8+ T lymphocytes, thus promoting an efficient antitumor immune response." (PMID 33212982, 2020). "Tregs that mainly differentiate from the naïve T-cell fraction to suppress excessive activation of T cells are described as CD25+ FOXP3+ CD4 T cells and function to suppress antitumor immunity by effector T cells in the tumor microenvironment." (PMID 32707672, 2020). "While T-bet ablation restricted the production of IFN-γ, loss of Blimp-1 prevented GzmB expression in response to IL-2, suggesting that two independent programmes required for the polyfunctionality of tumour-reactive cytotoxic CD4+ T cells." (PMID 32680511, 2020). "On the contrary, tumor-infiltrating Vδ1 T cells promoted tumor development by secreting IL-17 and inhibiting the maturation of CD4+/CD8+ T cells and DC." (PMID 33664732, 2020). "Of note, tumor-homing CD4+ TRM are more potent producers of TNF and IFN-γ compared with other tumor infiltrating T cells." (PMID 32106536, 2020). "In conclusion, this study showed that tumour grade correlated significantly with the overall dysfunction of CD4 and CD8 T cells and the efficacy of nivolumab monotherapy." (PMID 32277125, 2020). "Assuming that the tumor-expanded clones are the tumor-specific ones, this observation underscores an ongoing antitumor response, leading to an accumulation of tumor-specific CD4+ T cells in the tumor." (PMID 32601304, 2020). "We provide evidence that macrophage-driven ICB resistance is established by CD4 T cell suppression and Treg expansion in the tumor microenvironment via the PD-L1/PD-1/CD80 axis." (PMID 32071302, 2020). "CD8-positive T cells have been reported to have a greater role in the tumor immune environment than CD4-positive T cells." (PMID 32751195, 2020). "Traditionally, CD4+ Th1 cells are critical mediators for facilitating sustained anti-tumor responses." (PMID 32850346, 2020).
tumor (continued). "Developing CD4 T-cell based therapy comes with the technical challenge that although they can kill tumour cells, their primary mode of action is by engaging with other players in the immune system to orchestrate a broad attack of the tumour." (PMID 31915853, 2020). "Tumor-derived exosomes were shown to mediate the conversion of CD4+ CD25− T cells into CD4+ CD25high FOXP3+ regulatory T cells with enhanced expression of Fas ligand, IL-10, TGF-β1, CTLA-4, granzyme B, and perforin." (PMID 32499786, 2020). "CD4+ T helper 1 (Th1) cells mediate anti-tumor effects with the help of CD8+ T cells, hence, elevated numbers of CD4+ T helper 1 cells in the TME correlate with a positive clinical outcome in various human tumors (rev." (PMID 33255584, 2020). "Other studies also showed the abundance of CD8+ T cells within the tumor, while more CD4+ T cells were found in the tumor–liver interface, and an association between longer overall survival and the presence of tumor-infiltrating CD4+ or CD8+ T cells." (PMID 33212880, 2020). "Recently, we20–23 and others have shown that antigen-specific IL9-secreting (CD4+ Th9 or CD8+ Tc9) T cells are distinct subsets with stronger antitumor efficacy in murine tumor models compared to Th1, Th17, or Tc1/CTLs, respectively." (PMID 33214555, 2020). "Estimate the Proportion of Immune and Cancer cells, a computer-based tool for cell fraction analysis in a tumor, can evaluate fractions of immune cells (B cells, CD4 T cells, CD8 T cells, macrophages, and NK cells), CAFs, and endothelial cells." (PMID 33101367, 2020). "Higher PD1+ CTLs, PD1+CD4+ helper T cells (PD1+TCONV) and all PD1+ T cells in sTILs, tTILs and total stromal and tumor TILS (s+tTIL) were all associated with better prognosis." (PMID 32150594, 2020). "Among the tumor-infiltrating CD4 T cells, essentially all of the Foxp3+ population expressed high levels of cell surface CTLA-4." (PMID 31991588, 2020). "Specifically, cryo-thermal therapy-induced IL-6-rich acute pro-inflammatory response promotes DC phenotypic maturation, CD4(+) T cell differentiation, and Th1 anti-tumor immunity." (PMID 33240283, 2020). "TAMs frequently express PD-L1 and are capable of inhibiting the function of tumor-infiltrating CD4 and CD8 T cells through PD-L1/PD1 interaction." (PMID 31811337, 2020). "Especially, FOXP3+ regulatory T cells, which are also known as CD4+CD25+ Tregs, have suppressive effects on the anti-tumor immunity, and have been associated with poor clinical outcome." (PMID 32401825, 2020). "The observed increase in tumor rejection specifically required CD4+ T cell priming in the lymph node, as FTY720 blockade of lymph node egress prevented the anti-tumor immune response." (PMID 32508825, 2020). "We identified a large population of CD3+ CD4- CD8- T cells infiltrating the tumours of both the B16-OVA and CT26 models, as has previously been published." (PMID 33292783, 2020). "The complex array of functions by CD4 T cells in relation to anti-tumor immunity has been reviewed recently." (PMID 32630460, 2020). "An incisional biopsy of the oral mass was performed, the immunohistochemistry showed that the tumor cells tested positive for myeloperoxidase, CD4, BCL-2, KI-67." (PMID 33120806, 2020). "Of importance, activating CD4+ T cells in addition to neoantigen-specific CTLs leads to enhanced anti-tumor responses." (PMID 33298945, 2020). "T-cell exhaustion (CD8+ PD-1+/CTLA-4+) and treatment-induced depletion of regulatory T-cells (CD4+ Foxp3+/CTLA-4+) was seen in tumor or blood in 5/5 patients with clinical benefit, but only in one non-responder." (PMID 32681091, 2020). "These HDC+ BMMCs support tumor infiltration of CD4+ FOXP3+ Tregs and strongly support colonic tumorigenesis of CRC." (PMID 33419310, 2020). "Investigations showed that C2 influenced HCC prognosis via several mechanisms, including higher levels of tumor infiltrating CD4+ T and M0 macrophage cells in HCC patients with higher and lower levels of C2, respectively." (PMID 33718121, 2020).
tumor (continued). "Some types of CD4+ T cells impair the functions of cytotoxic T lymphocytes to promote the tumor development, while some types of CD4+ T cells induce the activation of cytotoxic T lymphocytes to exert antitumor immune response." (PMID 32206449, 2020). "We found that KLRB1, SIT1, and GZMM were negatively correlated with tumor purity and positively correlated with the infiltration of B cells, CD4 T cells, CD8 T cells, neutrophils, macrophages, and dendritic cells." (PMID 33164640, 2020). "Relative to saline-injected long-term survivors and age-matched naive tumor-implanted mice, we observed significant increases in the number of total T-cells (CD3+) and CD4+ T-cells in tumor-rechallenged long-term survivors." (PMID 33002018, 2020). "CD4 T cells display a large degree of plasticity to differentiate into Th1, Th2, Th17, and regulatory T cells (Tregs) in response to different tumor environments." (PMID 33240283, 2020). "Collectively, these results indicate that NNT-AS1 activates the TGF-β signaling pathway and thus inhibits CD4 T cell tumor infiltration in HCC." (PMID 33426064, 2020). "A decrease of CD4 to CD8 ratio in prostate tissue was reported in a cohort of PC patients following cryo-ablation of tumor nodes reflecting a restoration of T cell homeostasis in response to therapy." (PMID 33245727, 2020). "With regard to Tregs, migration of CD4+Foxp3+ T cells to the tumor microenvironment is an independent factor for poor prognosis." (PMID 33121123, 2020). "As this is a mechanism by which CD4+ Tregs mediate suppression and the propagation of primary infectious tolerance, it is also likely that this is a means by which tumor-derived EVs can mediate infectious tolerance within the TME." (PMID 32983104, 2020). "For example, cytotoxic CD8 T cells and CD4 helper T cells target antigenic tumor cells to prevent tumor growth." (PMID 32328190, 2020). "We report that T cell CD5 levels were higher in CD4+ T cells than in CD8+ T cells in 4T1 tumor-bearing mice, and that high CD5 levels on CD4+ T cells were maintained in peripheral organs (spleen and lymph nodes)." (PMID 33584650, 2020). "In the tumour microenvironment, we and others have shown that CD4+ and CD8+ T cells, myeloid cells and B cells are mainly located in the stroma of tumours, whereas CD8+ T cells can be found in both areas." (PMID 32249277, 2020). "One possible explanation is that abundant CD4+ CD25+ regulatory T cells were activated by tumor‐derived TGF‐β1, which creates a robust inhibitory network in solid tumors." (PMID 32160402, 2020). "The primary role of CD4+ helper T cells in tumor response is to assist in the activation of CD8+ T cell mediated cell killing." (PMID 33344239, 2020). "Combined therapy significantly inhibited tumor growth in comparison to monotherapy and the effects of therapy were CD4 T and CD8 T cell dependent." (PMID 33167311, 2020). "CD4+ T cells also support recruitment of CD8+ T cells to the tumor site, maintenance, and expansion of a CD8+ T cell memory response." (PMID 32594569, 2020). "And mature DCs then promote Th2 differentiation of naïve CD4 T cells and induce CD4+ T cells to secrete type 2 cytokines such as IL-13, contributing to tumor development." (PMID 32351590, 2020). "Data on the total tumor density, density in the tumor stroma and density in tumor epithelial areas of cells positive for CD4, FoxP3 and CD45RO were therefore collected from the CD8a-high cases of the U-CAN study population." (PMID 33153037, 2020). "Increasing evidence now suggests a vital role of CD4+ T cells in tumor protection, driving several anti-tumor mechanisms." (PMID 33383959, 2020). "Taken together, CD4 T and NK cells seem to play a relevant role for a successful anti-tumor antibody therapy in SK-BR-3 based HTM." (PMID 32799890, 2020). "cDC1s are present in peripheral tissues where they capture tumor antigens and, after migration to tumor‐draining lymph nodes, activate antitumor CD4+ and CD8+ T cells." (PMID 33282290, 2020).